IGLON5 (IgLON family member 5)
Synonyms: LOC402665
Tractability: Antibody: UniProt places it where antibodies can reach, with high confidence; UniProt predicts a signal peptide or a membrane-spanning region; its Gene Ontology location is reachable by antibodies, with medium confidence. PROTAC: its protein half-life has been measured.
Gene: Protein-coding gene on chromosome 19 (51,311,644 to 51,330,891, forward strand). Ensembl gene ENSG00000142549.
Subcellular location: Secreted
Gene Ontology:
Biological process: heterophilic cell-cell adhesion; regulation of synapse assembly; neuron recognition
Cellular component: plasma membrane; extracellular region
Genetic constraint (gnomAD): Loss-of-function variants: 15 observed, 27.92 expected, observed/expected ratio (o/e) 0.54, 90% interval 0.36 to 0.83. The upper end of that interval is the gene's LOEUF score, 0.83, which puts it in group 3 of 6, group 1 being the genes least tolerant of losing a copy. Missense variants: 333 observed, 390.46 expected, observed/expected ratio (o/e) 0.85, 90% interval 0.78 to 0.93. Synonymous variants: 189 observed, 176.37 expected, observed/expected ratio (o/e) 1.07, 90% interval 0.95 to 1.21.
Homologues: Orthologues: chimpanzee IGLON5 (100% identical), mouse Iglon5 (98% identical), dog IGLON5 (98% identical), guinea pig IGLON5 (98% identical), rat Iglon5 (92% identical), macaque IGLON5 (89% identical), rabbit IGLON5 (88% identical), tropical clawed frog iglon5 (59% identical), zebrafish iglon5 (51% identical), Drosophila melanogaster DIP-zeta (28% identical), Caenorhabditis elegans rig-5 (28% identical), Drosophila melanogaster klg (28% identical), and 10 more. Paralogues in human: OPCML (48% identical), NTM (47% identical), LSAMP (46% identical), NEGR1 (41% identical), IGSF5 (15% identical).
Diseases named in the same sentence as IGLON5 in open-access papers:
IGLON5 is named in the same sentence as 134 diseases in open-access papers, as found by Europe PMC text mining. Sharing a sentence is not in itself a finding about the gene and the disease. The quoted sentences say what the papers report.
encephalitis (33 papers, 2016 to 2026). An acute inflammatory process affecting the brain parenchyma. "Sleep disturbances are often frequent and severe, particularly in anti-NMDA, anti-LGI1 and anti-IgLON5 encephalitis, and the associated fatigue is an accurate predictor of poor long-term QoL." (PMID 40514744, 2025). "In another case, a 16-year-old girl with severe Mycoplasma pneumonia developed anti-IgLON5 antibody-associated encephalitis, with symptoms of cough, fever, and neuropsychiatric symptoms." (PMID 40546543, 2025). "The management of Anti-IgLON5 antibody-associated encephalitis lacks standardized guidelines, though immunotherapy is commonly employed." (PMID 39224609, 2024). "The clinical presentation of anti-IgLON5 antibody-related encephalitis is diverse, with sleep disturbances as the hallmark symptom." (PMID 38765268, 2024). "Our data expand the list of encephalitis-derived autoantibodies that mediate neurodegenerative changes in cultured neurons such as anti-GluR3B IgG and anti-IgLON5, and support the causative role of autoantibodies in autoimmune encephalitis." (PMID 36613687, 2022). "Serum and CSF IgLON5 antibodies provide another example, as they can induce an encephalitis often associated with cognitive dysfunction including figural memory deficits in addition to neurological deficits." (PMID 33026492, 2021). "Among these syndromes, IgLON-5–associated encephalitis has been linked to IgG1 class and inflammatory processes." (PMID 32982676, 2020). "IgLON5-associated encephalitis is a relatively new autoimmune encephalopathy that can present with various neurological symptoms." (PMID 29867738, 2018). "The hallmark of anti-IgLON5 associated encephalitis is parasomnia involving REM and non REM sleep with stridor, abnormal sleep behavior, e.g., patients mimic activities of daily living, and sleep apnoea." (PMID 30524441, 2018). "Patients diagnosed with anti-IGLON5 syndrome followed by HE and GlyR antibody associated encephalitis had the biggest latency in receiving a diagnosis and treatment with immunosuppressive agents." (PMID 30524441, 2018). "In parallel, autoimmune encephalitides, like the rare Anti-IgLON5 antibody-associated encephalitis, are a diverse set of disorders marked by immune-mediated inflammation of the central nervous system, posing considerable diagnostic and therapeutic complexities." (PMID 39224609, 2024). "Anti-IgLON5 antibody-associated encephalitis is an exceedingly rare subtype of AE." (PMID 39224609, 2024). "Consequently, anti-IgLON5 antibody-related encephalitis is also considered to be linked with neurodegeneration." (PMID 38765268, 2024). "This intricate case of a 16-year-old female presents a unique convergence of severe Mycoplasma pneumoniae pneumonia (MPP) and Anti-IgLON5 antibody-associated encephalitis, underscoring the diagnostic and therapeutic challenges intrinsic to such complex clinical manifestations." (PMID 39224609, 2024). "IgLON-5–associated encephalitis may be related to the induction of microglial activation by perivascular CD8 T cells." (PMID 32982676, 2020). "IgLON5-associated encephalitis is a syndrome with different clinical presentations consisting of sleep dysfunction, bulbar dysfunction, chorea, and progressive supranuclear palsy-like symptoms whereas dysautonomy and cognitive decline usually appear in later stages of the disease." (PMID 29867738, 2018). "However, one exception would be when anti-IgLON5-associated encephalitis is suspected, as the clinical course could be protracted." (PMID 37954587, 2023). "Although retinal involvement is rarely reported, these findings suggest a possible role for the retina in the pathophysiology of anti-IgLON5 encephalitis." (PMID 41755996, 2026). "This article presents an analysis and summary of the clinical data of two paediatric patients with anti-IgLON5 antibody-related encephalitis." (PMID 38765268, 2024).
encephalitis (continued). "Anti-N-methyl-D-aspartate (NMDA) receptor encephalitis and anti-IgLON5 encephalitis are specific autoimmune encephalitides that have been documented to involve the vocal cords, manifesting complete paralysis, palsy, or a degree of dysphonia." (PMID 39664290, 2024). "It has been well-documented that anti-NMDA receptor encephalitis and anti-IgLON5 encephalitis have some laryngeal involvement." (PMID 39664290, 2024). "Paediatric cases of anti-IgLON5 antibody-related encephalitis similarly present sleep disturbances as a core symptom, alongside various forms of movement disorders." (PMID 38765268, 2024). "In anti IgLON5 Encephalitis, there is in vivo evidence of the accumulation of p-Tau and death of nigrostriatal dopaminergic neurons leading to persistent motor impairment." (PMID 39651491, 2024). "This study aims to enhance the understanding of paediatric anti-IgLON5 antibody-related encephalitis by summarising its clinical and therapeutic characteristics." (PMID 38765268, 2024). "Although the pathogenesis of anti-IgLON5 antibody-related encephalitis differs from other types of autoimmune encephalitis and tends to have a longer disease course, it is still associated with viral infections." (PMID 38765268, 2024). "A retrospective analysis was conducted on two paediatric patients diagnosed with anti-IgLON5 antibody-related encephalitis at Hunan Children’s Hospital from August 2022 to November 2023." (PMID 38765268, 2024). "In children, anti-IgLON5 antibody-related encephalitis primarily presents with sleep disturbances and various forms of movement disorders, and there is partial effectiveness of immunotherapy." (PMID 38765268, 2024). "In summary, anti-IgLON5 antibody-related encephalitis is a rare and relatively unique form of autoimmune encephalitis." (PMID 38765268, 2024). "anti-IgLON5 antibody-related encephalitis predominantly affects middle-aged and elderly individuals aged 50–60 years, with no significant gender disparity observed." (PMID 38765268, 2024). "Our case firstly reports a patient diagnosed with anti-AMPAR encephalitis overlapped with anti-IgLON5 disease post HSE." (PMID 38259458, 2023). "We describe a patient diagnosed with anti-AMPAR encephalitis overlapped with anti-IgLON5 disease after HSV-1 infection." (PMID 38259458, 2023). "Limbic encephalitis is a highly uncommon occurrence involving anti-alpha-amino-3-hydroxy-5-methyl-4-isoxazolepropionic acid receptor (AMPAR) encephalitis and anti-IgLON family member 5 (IgLON5) disease, both belonging to the rare category." (PMID 38259458, 2023). "As far as we know, this is the first report showing that a patient diagnosed with AMPAR encephalitis overlapped with anti-IgLON5 disease post herpes simplex virus encephalitis (HSE), which helps to broaden the range of this uncommon autoimmune disease." (PMID 38259458, 2023). "In our literature cohort, one additional patient with anti-GABAAR encephalitis had Hodgkin lymphoma and one with anti-IgLON5 autoimmunity was affected by Langerhans cell histiocytosis." (PMID 35515348, 2022). "Twenty-eight were of anti-NMDA-receptor encephalitis with other cases associated with antibodies against LGi1, Caspr2, glycine receptor, DPPX, GABAB receptor, IgLON5, GFAP, and SOX1." (PMID 33692738, 2021). "Six patients were diagnosed with anti-IgLON5 antibody encephalitis at Toulouse University Hospital." (PMID 41755996, 2026). "This case emphasizes the significance of anti-IgLON5 encephalitis in the differential diagnosis of complex sleep disorders, while also providing new insights and experiences regarding the evaluation of immune-modulatory therapy in the treatment of anti-IgLON5 encephalitis through 18F-FDG PET-CT." (PMID 41808898, 2026).
encephalitis (continued). "This patient, diagnosed with Langerhans Cell Histiocytosis (LCH), developed neurological symptoms during the disease and was diagnosed with anti-IgLON5 antibody-related encephalitis following the detection of positive anti-IgLON5 antibodies at 1: 30 in the serum." (PMID 38765268, 2024). "Literature on anti-IgLON5 encephalitis imaging is also very limited." (PMID 38327544, 2024). "A thorough review of both domestic and international literature revealed no reported cases of MP infection inducing Anti-IgLON5 antibody-associated encephalitis." (PMID 39224609, 2024). "Finally, we review the clinical and pathological features of IgLON5 antibodies-related encephalitis, a unique model of the relationship between antibodies and neurodegeneration." (PMID 36979644, 2023). "However, concurrent sleep abnormalities like parasomnia, sleep apnea, insomnia, or excessive daytime sleepiness are red flags for IgLON5-related disease in nearly all patients with IgLON5 encephalitis." (PMID 33324912, 2020). "(Note: Anti-IgLON5 and anti-GFAP encephalitis cases were excluded from tabular presentation due to limited sample size [n = 2 each])." (PMID 40170898, 2025). "Anti-IgLON5 disease usually has a protracted clinical course and is diagnosed many months after symptom onset in contrast to anti-NMDAR or anti-AMPAR encephalitis that usually has a rapid presentation in days or weeks." (PMID 35690819, 2022). "Among them, 35 (42.2%) patients were diagnosed with anti-NMDAR encephalitis, 24 (28.9%) with anti-LGl1 encephalitis, 13 (15.7%) with anti-GABABR encephalitis, eight with anti-CASPR2 encephalitis, two with anti-IgLON5, anti-DPPX and anti-mGluR5 encephalitis, and one with anti-AMPAR1 encephalitis." (PMID 40977726, 2025). "Patients with anti-NMDAR encephalitis and other rarer subtypes like anti-GABABR, anti-AMPAR, and anti-DPPX encephalitis, can show OCB positive in CSF and /or serum, but patients with anti-LGI1, anti-IgLON5, anti-CASPR2, and anti-GlyR antibodies are rarely OCB positive." (PMID 35937071, 2022). "The cases of anti-IgLON5 encephalitis and anti-GFAP encephalitis both required ICU admission." (PMID 33692738, 2021).
autoimmune encephalitis (24 papers, 2020 to 2026). Inflammation of the brain secondary to an immune response triggered by the body itself. "Lastly, antibodies against the IgLON member IgLON5 (IgLON Family Member 5) have been associated with autoimmune encephalitis." (PMID 37895235, 2023). "Five (4.8%) patients could not be clearly classified based on ASFA recommendations (polytrauma-associated coagulopathy, anti-IgLON5-associated encephalopathy, polyradiculoneuritis, acute demyelinating neuropathy, autoimmune encephalitis)." (PMID 37109212, 2023). "Anti-IgLON5 disease is an autoimmune encephalitis that presents with a heterogenous clinical phenotype, including sleep disorders, movement abnormalities and bulbar involvement." (PMID 40650880, 2026). "Anti-IgLON5 disease is an autoimmune encephalitis with more chronic presentation including memory decline, sleep disorder, bulbar symptoms and movement disorder." (PMID 40930030, 2025). "Introduction of Autoimmune Encephalitis Treatment: The identification of IgLON5 antibodies indicated an autoimmune component, justifying the use of methylprednisolone, IVIG, and plasma exchange." (PMID 39224609, 2024). "The confirmation of Mycoplasma pneumoniae through genetic testing and serology, combined with the detection of IgLON5 antibodies, supported a diagnosis of Mycoplasma pneumoniae pneumonia complicated by autoimmune encephalitis." (PMID 39224609, 2024). "Among autoimmune encephalitis disorders, anti-IgLON5 disease is a rare autoimmune encephalitis characterized by neurodegenerative pathology." (PMID 37760924, 2023). "Until now, autoimmune encephalitis with both anti-IgLON5 and anti-LGI1 receptor antibodies following COVID-19 is rarely reported." (PMID 37383232, 2023). "Two of our patients (J-17_01 and J-17_17) were diagnosed by laboratory findings (Eurimmun, Lübeck) as suffering from anti-IgLON5 autoimmune encephalitis." (PMID 37603074, 2023). "Anti-IgLON family member 5 (IgLON5) disease is a rare autoimmune encephalitis, characterized by sleep problems, cognitive decline, gait abnormalities, and bulbar dysfunction." (PMID 37383232, 2023). "Yet, patients with LGI1 (the most common form of autoimmune encephalitis), CASPR2m and IgLON5 antibodies can present over long durations with minimal evidence of paraclinical investigation abnormalities, other than the autoantibody itself." (PMID 36441519, 2023). "Autoimmune encephalitis testing of blood and cerebrospinal fluid samples revealed positive IgLON5 antibodies (1:30), while antibodies against N-methyl-D-aspartate receptor (NMDAR), voltage-gated potassium channel (VGKC) complexes, Hu, Yo, and Ri were all negative." (PMID 39224609, 2024). "Anti-IgLON5 disease is an autoimmune encephalitis mediated by anti-IgLON5 antibodies." (PMID 37760924, 2023). "Many of the autoimmune encephalitis subgroups (anti-DPPX, anti-GABABR anti-IgLON5, anti-GFAP, and anti-SOX1) had an antibody present in both serum and CSF in 100% of cases." (PMID 33692738, 2021). "Represented in smaller but still significant numbers were other subgroups of autoimmune encephalitis with other antigenic targets including glycine receptor, LGi1, Caspr2, DPPX, GABA-B, IgLON5, GFAP, and SOX1." (PMID 33692738, 2021). "There were three or fewer cases of autoimmune encephalitis with antibodies directed against Caspr2, DPPX, GABABR, IgLON5, GFAP, and SOX1." (PMID 33692738, 2021). "The transfection cytology methods were used to detect autoimmune encephalitis antibodies (NMDAR, AMPAR1, AMPAR2, LGI1, CASPR2, GABABR, DPPX, IgLON5, GlyRα1, GABAARα1, GABAARβ3, mGluR1, mGluR5, D2R, Neurexin-3α, GAD65, KLHL11, gAChR, AQP4, MOG, GFAP) in CSF and serum." (PMID 40771880, 2025). "As a limitation, we did not perform screening for IgLON5 or other autoimmune encephalitis-related antibodies." (PMID 40233181, 2025). "Therefore, the patient was diagnosed with anti-IgLON5 disease and anti-LGI1 autoimmune encephalitis." (PMID 37383232, 2023).
autoimmune encephalitis (continued). "Although this has never been previously shown as an effect of anti-IgLON5 antibodies, changes in electrophysiological properties are a commonly described effect of antibodies of other subtypes of autoimmune encephalitis." (PMID 35690819, 2022). "Extended panels of autoimmune encephalitis autoantibodies performed in rat brains by IHC were negative (anti-NMDAR, AMPAR, GABABR, GABAAR, LGI1, CASPR2, mGluR1, mGluR2, mGluR5, DPPX, IgLON5, Neurexin)." (PMID 40150045, 2025).